GZMM (granzyme M)
Description:
Cleaves peptide substrates after methionine, leucine, and norleucine. Physiological substrates include EZR, alpha-tubulins and the apoptosis inhibitor BIRC5/Survivin. Promotes caspase activation and subsequent apoptosis of target cells.
Synonyms: MET1; LMET1
Tractability: Antibody: UniProt places it where antibodies can reach, with medium confidence; UniProt predicts a signal peptide or a membrane-spanning region; its Gene Ontology location is reachable by antibodies, with medium confidence. PROTAC: its protein half-life has been measured.
Target class: Enzyme; Hydrolase
Gene: Protein-coding gene on chromosome 19 (544,034 to 549,924, forward strand). Ensembl gene ENSG00000197540.
Subcellular location: Secreted; Cytoplasmic granule
Pathways (Reactome):
Immune System: Alternative complement activation
Gene Ontology:
Molecular function: protein binding; serine-type endopeptidase activity; serine-type peptidase activity; endopeptidase activity
Biological process: apoptotic process; protein maturation; proteolysis
Cellular component: extracellular region; membrane
Genetic constraint (gnomAD): Loss-of-function variants: 24 observed, 17.13 expected, observed/expected ratio (o/e) 1.4, 90% interval 1.01 to 1.86. The synonymous counts are far from expectation, so gnomAD's model fits this gene poorly and the ratio says little. Missense variants: 373 observed, 305.92 expected, observed/expected ratio (o/e) 1.22, 90% interval 1.12 to 1.33. Synonymous variants: 178 observed, 137.21 expected, observed/expected ratio (o/e) 1.3, 90% interval 1.15 to 1.47.
Homologues: Orthologues: chimpanzee GZMM (97% identical), macaque GZMM (86% identical), mouse Gzmm (67% identical), rat Gzmm (65% identical), pig GZMM (63% identical). Paralogues in human: PRSS57 (40% identical), PRSS33 (34% identical), KLK15 (30% identical), PLG (30% identical), PRSS27 (30% identical), TMPRSS12 (29% identical), PLAT (28% identical), PRSS50 (28% identical), PRSS48 (28% identical), KLK9 (28% identical), OVCH1 (26% identical), PRSS37 (24% identical), and 2 more.
Diseases named in the same sentence as GZMM in open-access papers:
GZMM is named in the same sentence as 32 diseases in open-access papers, as found by Europe PMC text mining. Sharing a sentence is not in itself a finding about the gene and the disease. The quoted sentences say what the papers report.
breast cancer (26 papers, 2013 to 2025). A primary or metastatic malignant neoplasm involving the breast. "We also attempted to explore the significance of GZMM in human cancer cells and confirmed its expression in colon cancer, lung adenocarcinoma and breast cancer samples." (PMID 25788270, 2015). "In addition, in clinical samples of lung adenocarcinoma and breast cancer, GZMM expression was also identified." (PMID 25788270, 2015).
Sepsis (2 papers, 2020 to 2026). Sepsis is defined as life-threatening organ dysfunction caused by a dysregulated host response to infection. "Overall, the multifaceted study shed light on key roles played by these hub genes (especially DDX24 and GZMM) in the development of sepsis and will be useful references in diagnosing patients and estimating prognosis." (PMID 41948606, 2026). "Pending of validating the clinical significance of the presence of soluble Gzms in septic patients, studies in animal models in vivo indicate a key role for some Gzms like GzmA and GzmM in inflammation and sepsis." (PMID 32655547, 2020). "Recent studies have found that GzmA, GzmB, GzmK, and GzmM act as pro-inflammatory mediators and could be involved in the pathophysiology of sepsis." (PMID 32655547, 2020). "This would explain why GzmB deficiency does not protect from sepsis, but would not explain the increased resistance of GzmM deficient mice to endotoxicosis and the reduced coagulation activity observed in these mice." (PMID 32655547, 2020). "Since some Gzms like GzmA and GzmM seem to be inflammatory mediators responsible of the detrimental effects of LPS in sepsis, including TNF-α production, they also could contribute to altered endothelial permeability." (PMID 32655547, 2020).
ulcerative colitis (2 papers, 2016 to 2022). An inflammatory bowel disease involving the mucosal surface of the large intestine and rectum. "A recent study found that GZMM is also involved in the early stages of mucositis as GZMM knockout mice exhibit increased inflammation in a mouse model of ulcerative colitis." (PMID 35563668, 2022).
Arthritis (1 paper, 2021). Inflammation of a joint. "As described afore, GzmA inhibition could repress CHIKV-mediated arthritis, and GzmM might also contribute to inflammation-mediated damage." (PMID 34529743, 2021).
cervical cancer (1 paper, 2015). A primary or metastatic malignant neoplasm involving the cervix. "Similarly, GZMM was found to be expressed in human the cervical cancer cell line HeLa at both the mRNA and protein levels by chance, thus, its function was not well investigated." (PMID 25788270, 2015).
colon carcinoma (1 paper, 2015). "We next analyzed the expression of GZMM by immunohistochemistry staining in 90 surgical samples of human primary colon carcinoma and matching normal regions adjacent to the tumor." (PMID 25788270, 2015). "We previously detected murine GZMM expression in the murine colon cancer cell line CT26 through microarray gene expression analysis." (PMID 25788270, 2015).
leukoplakia (1 paper, 2021). A white patch or plaque on a mucous membrane that cannot be characterized clinically or pathologically as any other disease. "Gene set analysis identified granzyme M as the most differentially expressed gene favoring the proliferative leukoplakia subgroup (log2 fold change, 1.93; Padj < 0.001)." (PMID 36860910, 2021).
ovarian carcinoma (1 paper, 2020). A malignant neoplasm originating from the surface ovarian epithelium. "In certain cancer types, different eQTL-lncRNAs pairs influence the same set of mRNA targets; for example, in ovarian cancer, two eQTL (2p25.2 and 7q34) eventually regulate the same set of mRNAs (FASLG, GZMM, PYHIN1 and TRAT1) but through different elncRNAs (AC092580.4 and TRBV11-2)." (PMID 33194770, 2020).
Parkinson disease (1 paper, 2024). A progressive degenerative disorder of the central nervous system characterized by loss of dopamine producing neurons in the substantia nigra and the presence of Lewy bodies in the substantia nigra and locus coeruleus. "Among CD8+ genes that scaled proportionally with the PRS for Parkinson’s disease, top genes included GZMM and IL2RB." (PMID 38590520, 2024).
tumor (50 papers, 2012 to 2025). "In this study, in CT26 and 4T1 cells, we found that GZMM is positively related to IL-6 and VEGF release, which indicates that GZMM may be involved in tumor-associated inflammatory response and angiogenesis." (PMID 25788270, 2015). "This was seen in conjunction with upregulation of genes associated with tumor-infiltrating lymphocyte (TIL) cytotoxicity (CD3G, SAP, PRF1, GZMM and GZMK)." (PMID 34084172, 2021). "Concurrently, we observed increased expression of genes associated with tumor infiltrating lymphocyte (TIL) cytotoxicity (CD3G, SAP, PRF1, GZMM and GZMK)." (PMID 34084172, 2021). "In fact, our data on TILs shows prominent upregulation of perforin 1 (PRF1), granzymes K (GZMK) and M (GZMM), which are key for lymphocyte anti-tumor cytotoxicity." (PMID 34084172, 2021). "GZMM is one of many serine proteases housed in granules released from cytotoxic lymphocytes which later enter tumor cells via perforin to activate cell death pathways." (PMID 36860910, 2021). "Overexpressed IRF-3 drove NK cells to express type I interferon, chemokine and costimulatory molecules, hence enhancing their tumor-suppressing functions, including cell proliferation, release of perforin and granzyme M, and cytotoxicity toward tumor cells." (PMID 32489584, 2020). "We found that KLRB1, SIT1, and GZMM were negatively correlated with tumor purity and positively correlated with the infiltration of B cells, CD4 T cells, CD8 T cells, neutrophils, macrophages, and dendritic cells." (PMID 33164640, 2020). "TIMER analysis revealed that KLRB1, SIT1, and GZMM were negatively correlated with tumor purity and positively correlated with the infiltration of B cells, neutrophils, macrophages, CD4 T cells, CD8 T cells, and dendritic cells." (PMID 33164640, 2020). "SERPINB4 is expressed at high levels in many tumor cells, and is known to inactivate granzyme M, an enzyme involved in tumor cell death." (PMID 30038719, 2018). "Our study revealed the role of granzyme M expressed by tumor in chemoresistance, invasion, metastasis and EMT." (PMID 25788270, 2015). "Accordingly, we focus on a unique gene termed granzyme M (GZMM) that was upregulated in slow-cycling tumor cells." (PMID 25788270, 2015). "Recent data demonstrated that overexpression of SERPINB4 in tumor cells inhibited recombinant granzyme M-induced as well as NK cell-mediated cell death." (PMID 24710357, 2014). "In addition, anti-cancer immune-related genes were observed, e.g., SERPINB4 is highly expressed in cancer cells and inactivates anti-tumor enzymes such as granzyme M." (PMID 38203315, 2023). "The protein of SERPINB4 can inactivate granzyme M, an enzyme that kills tumor cells." (PMID 35439935, 2022). "However, we detected granzyme M expression in murine and human cancer cell lines and human tumor samples in our study." (PMID 25788270, 2015). "We hypothesized that GZMM, as a serine protease, may promote tumor invasion by hydrolyzing its substrates contained in matrigel." (PMID 25788270, 2015). "A western blot analysis revealed that the GZMM protein was also present in those tumor cells." (PMID 25788270, 2015). "Most importantly, granzyme M facilitated tumor growth and metastasis in vivo." (PMID 25788270, 2015). "To explore whether the expression of GZMM in tumor cells is universal, we validated the expression of GZMM at both the mRNA and protein levels in several murine tumor cell lines using Balb/c lymphocytes as the positive control." (PMID 25788270, 2015). "Likewise, knockdown of GZMM in LLC delayed the tumor growth in C57 mice as displayed." (PMID 25788270, 2015). "The CD8+ T cells were activated post-NICT, then stimulated CD16+ NK cell activation, and achieved tumor cell killing by cytokines (e.g., IFN-γ and GZMM)." (PMID 39076970, 2024).
tumor (continued). "Consistently, the tumor-infiltrating GZMAhigh NK subcluster expressing a high level of cytotoxic genes (GZMA, GZMB, GZMK, GZMM, GZMH, PRF1, and GNLY) and FASL and TRAIL genes was most enriched in the PD-1+SMI group." (PMID 37430270, 2023). "In comparison to the adjacent non-tumor tissues, the CD56dimCD16hi NK cells within tumors showed a decrease in the expression of cytotoxic effector genes, such as PRF1 and most granzymes (GZMA, GZMH, and GZMM), except for GZMB." (PMID 38552055, 2024). "Then, we compared the expression of TBX21, EOMES, IFN-γ, and GZMM in the ESCA tumor tissue among the NICT, NCT, and NONE groups by immunofluorescent staining and qRT-PCR." (PMID 39076970, 2024). "The increased expression of cytotoxic effector molecules GZMA, GZMB, GZMH, GZMM, GNLY, NKG7, and PRF178 but also of the thioredoxin function inhibitor TXNIP79, demonstrates a potent effector capacity to eliminate malignant cells and suppress tumor growth." (PMID 33602930, 2021). "As for T cell related cytotoxins, essential in tumor killing, stacked FPKM of 8 genes (PRF1, GZMM, GZMK, GZMH, GZMB, GZMA, FASLG, and FAS) demonstrated that these genes were more highly expressed 1.7-fold (P = 0.037) in IFNγ positive tumors compared to IFNγ negative tumors." (PMID 32265897, 2020).
cancer (14 papers, 2011 to 2025). A tumor composed of atypical neoplastic, often pleomorphic cells that invade other tissues. "Granzyme M induced the epithelial-mesenchymal transition (EMT) in cancer cells associated with STAT3 activation." (PMID 25788270, 2015). "We found that GZMM is expressed in common murine carcinoma cell lines, human cancer cell lines and clinical carcinoma samples, which largely expand our knowledge of this so-termed “orphan” granzyme." (PMID 25788270, 2015). "All of these observations implied the considerable function of GZMM in facilitating cancer cell metastasis in vivo." (PMID 25788270, 2015). "In the present study, we took a directed approach to explore the expression and function of GZMM in cancer cells for the first time." (PMID 25788270, 2015). "The results revealed GZMM was abnormally expressed in most carcinoma cells but rarely in adjacent normal epithelial cells." (PMID 25788270, 2015). "Consequently, we were encouraged by these findings to investigate the expression of GZMM in solid tumor cells and its function in cancer progression." (PMID 25788270, 2015). "To assess whether the expression of GZMM is dependent on a specific type of cancer cell line, we performed the measurement and found that the expression of GZMM is conserved in several types of murine and human malignant cell lines." (PMID 25788270, 2015). "If it can be validated, GZMM may be a novel target for cancer therapy with good prospects." (PMID 25788270, 2015). "Many of these genes function in inflammation (CXCR3, EOMES, IL18R1, GZMM, IL2rb), metastases (CXCR3, BUB1), poor outcome cancers (EOMES, BUB1), or stem cells (EOMES, BUB1)." (PMID 22053823, 2011). "Notably, the GZMA CD4 T cell subset exhibited elevated expression of genes associated with effector and cytolytic functions in CD4 T cells, including GZMA, GZMH, GZMM, and PRDM1, while also showing moderate expression of anti-cancer-related genes such as IFNG, PRF1, and TNFSF10." (PMID 40959273, 2025).
GZMM also shares sentences with these, for which no sentence is quoted: infection (11 papers); Obesity (3); melanoma (2); osteosarcoma (2); actinic keratosis (1); bacterial infection (1); breast tumors (1); endometrial cancer (1); glioblastoma (1); head and neck cancer (1); Immunodeficiency (1); lung adenocarcinoma (1); mucositis (1); myeloma (1); retinoblastoma (1); squamous cell carcinoma (1); sterility (1); thyroid carcinoma (1); triple-negative breast carcinoma (1); viral infections (1); Zinc deficiency (1).